MIR4254 (microRNA 4254)
Synonyms: hsa-mir-4254
Gene: MicroRNA gene on chromosome 1 (31,758,660 to 31,758,735, reverse strand). Ensembl gene ENSG00000266580.
Homologues: Orthologues: chimpanzee MIR4254 (100% identical).